BCL2 (BCL2 apoptosis regulator)
Diseases named in the same sentence as BCL2 in open-access papers (continued):
Sharing a sentence is not in itself a finding about the gene and the disease.
leukemia (continued). "Azacitidine inhibits the prosurvival proteins MCL1 and BCL-XL, thereby increasing the dependence of leukemia cells on BCL2, which is directly targeted by venetoclax." (PMID 37046645, 2023). "The expression of the anti-apoptotic protein Bcl-2 was also significantly decreased in a dose-dependent manner (p < 0.05); its expression was significantly lower in hesperetin-treated leukemia cells than in control cells." (PMID 36826047, 2023). "Overexpression of circ_0003420 considerably inhibited the proliferative ability and viability of leukemia cells but promoted cell apoptosis through regulation of Bcl-2/Bax ratio and cleaved caspase-3." (PMID 37124518, 2023). "In BCP-ALL, heterogeneous responses have been observed and the mitochondrial dependence on BCL-2 is a marker of response for the anti-leukemia activity of venetoclax." (PMID 35031695, 2022). "The upregulation of PRKCA has shown to have implications in OSCC, and attributed to chemoresistance by the phosphorylation of BCL2 in leukemia." (PMID 36703917, 2022). "For example, Blombery and colleagues described 11 patients with progressive CLL who had leukemia cells with BCL2G101V and other oligoclonal BCL2 mutations." (PMID 35418613, 2022). "In leukemia cells, the treatment with venetoclax (BCL2 inhibitor) impacts the tricarboxylic acid by inhibiting amino acid metabolism and contributing to the selective elimination of this cell population." (PMID 36294912, 2022). "Our experiments demonstrate that guanidines are cytotoxic against human leukemia U-937 cells that overexpress Bcl-2." (PMID 36555165, 2022). "The 3D structure of the isochamaejasmenin was highly similar to that of the Bcl-2 ligand (-)-gossypol, which can induce apoptosis in human leukemia HL-60 and K562 cells via the Bcl-2 cell apoptosis pathway." (PMID 36059675, 2022). "Another study reported that Bcl-2 preserve the mitochondrial membrane and binds to Bax in order to inhibit apoptosis in leukemias." (PMID 36699321, 2022). "This miRNA has been associated with drug resistance, and it is an essential driver of KMT2A-AFF1 leukemia, integrated with the aberrant overexpression of key downstream targets, i.e., the antiapoptotic factor BCL2 and proto-oncogene MYC." (PMID 36010971, 2022). "Bcl-2, which inhibits the intrinsic apoptosis pathway, is overexpressed in AML cells, and VEN induces apoptosis in leukemia cells dependent on BCL-2 for survival." (PMID 35433414, 2022). "BCL-2 is overexpressed in leukemia stem cells and the use of a specific inhibitor of BCL-2, venetoclax, combined with azacitidine, resulted in disease remission in acute myeloid leukemia by CSC targeting." (PMID 36498571, 2022). "SuperDendrix also finds associations for three downstream targets of TCF3 and IRF4 transcription factors: BCL2 and {leukemia, myeloma, MEF2B(A)}, PIM2 and myeloma, and POU2AF1 and Myeloma,MEF2BA." (PMID 35382456, 2022). "One of them used a more stringent sorting approach to profile the transcriptome of leukemia initiating cells and reported increased BCL2 and CXCR4 signaling in relapse." (PMID 35986270, 2022). "Venetoclax is a selective inhibitor of the anti-apoptosis factor B-cell lymphoma 2 (BCL2), which has been revealed to abundantly express in leukemia stem cells." (PMID 34568973, 2022). "Our findings suggest that MEK/Bcl‐2 inhibition has therapeutic potential in leukemia and myeloma, and demonstrate that protein expression levels can serve as predictive biomarkers for treatment sensitivities." (PMID 34861096, 2022). "Solid cancers have shown to be less dependent on BCL-2 as compared to leukemias explaining why BH3-mimetics showed little clinical activity in solid tumors." (PMID 35443750, 2022). "Mcl-1 is an important antiapoptotic protein and plays a more important role than Bcl-2 in leukemia development and survival maintenance." (PMID 35443722, 2022).
leukemia (continued). "In summary, the combinatorial blockade of the EZH2 and BCL-2 shows a great synergistic anti-leukemia effect through upregulated PIK3IP1 and downregulated c-KIT." (PMID 36232694, 2022). "Venetoclax, which specifically targets BCL-2, achieves a wide range of anti-leukemia capabilities, partly due to the decreasing apoptotic threshold of AML cells." (PMID 35865470, 2022). "Given the pivotal role of BCL2 in the pathogenesis of CLL, different molecules have been designed to target BCL2 in this leukemia." (PMID 35207569, 2022). "Mouse models with Nup98 protein fusions exhibit increased apoptosis, and a zebrafish model of NUP98-HOXA9-driven leukemia upregulates Bcl2 to suppress apoptosis." (PMID 35107131, 2022). "Disrupted expression of BCL-2 protein contributes to the pathogenesis of almost all B cell lymphomas and leukemia." (PMID 35897737, 2022). "For instance, the m6A writer, METTL3 was found to promote the translation of c-MYC and BCL2 to accelerate leukemia progression by suppressing differentiation and apoptosis in acute myelocytic leukemia." (PMID 35646049, 2022). "SuperDendrix also identifies increased dependencies on PIK3CA and BCL2 in some of the same cancer types, including PIK3CA in myeloma and rhabdomyosarcoma and BCL2 in leukemia and myeloma." (PMID 35382456, 2022). "With venetoclax/ABT-199, the first of these BH3-mimetics targeting Bcl-2 has been approved for the treatment of leukemia, highlighting the potential of the Bcl-2 proteins as targets in anticancer therapy." (PMID 34374809, 2022). "Human T-lymphoblastic lymphoma/leukemia cells have shown to overexpress Bcl-2, accelerating malignant transformation by suppressing Myc-induced apoptosis." (PMID 35448666, 2022). "Brd4 is also a transcription factor for c‐Myc and Bcl2, and Brd4 inhibition induces apoptosis of leukemia cells." (PMID 35132816, 2022). "Glutaminase inhibition can promote leukemia cells to overcome drug resistance, and to be sensitive to BCL2 inhibitors, FMS-like tyrosine kinase 3 and other tyrosine kinase inhibitors." (PMID 36618700, 2022). "Several pre-clinical and clinical studies have indicated cooperative activity between MEK and Bcl-2 antagonists in solid tumors, MM, and leukemias (NCT03312530), (NCT02670044), (NCT04487106)." (PMID 36523963, 2022). "By downregulating MCL1 and inducing the expression of the pro-death proteins NOXA and PUMA, azacytidine inhibits synergistically the pro-survival proteins MCL1 and BCL-XL, increasing the dependence of leukemia cells on BCL-2." (PMID 36008542, 2022). "Although any experimentations reported an inhibitory effect performed by the molecule on oxidative stress via the stimulation of antioxidant molecules in tumor cells, other studies have demonstrated that Bcl-2 can stimulate ROS generation in leukemia cells." (PMID 36139768, 2022). "Inhibiting FAO has been shown to increase the Bax/Bcl-2 ratio and trigger apoptosis in leukemia and glioblastoma." (PMID 35742944, 2022). "Initial studies exploring the ability of Bcl-2 ASO to inhibit leukemia cell survival used a 20-base pair oligonucleotide complementary to the transcription initiation site of Bcl-2 mRNA." (PMID 35056993, 2022). "Literature elucidated that in HL-60 leukemia cells, BB promoted cell apoptosis by increasing caspase-8/9 expression and caspase-3 activation, then leading to Bcl-2 inhibition." (PMID 34771481, 2021). "The BCL-2/BCL-XL inhibitors ABT-737, ABT-263, and venetoclax induce apoptosis in vitro and in vivo in ALL subsets, including KMT2A-rearranged and TCF3-HLF ALL leukemia xenografts and human lymphoid tumors that overexpress BCL-2." (PMID 35008312, 2021).
leukemia (continued). "We next determined if BCL-2 downregulation in NK92MI cells affected reactivity against target cells using the human leukemia cell line K562." (PMID 34063475, 2021). "Our findings are consistent with recent studies showing the effectiveness of inhibiting overexpressed kinases and Bcl-2 proteins in leukaemia." (PMID 33581643, 2021). "Our results showed that the apoptosis proteins, cleaved caspase 3, cleaved caspase 9 and Bax, were aberrantly over-expressed after knocking down IL-1β in leukemia cells by siRNA, while Bcl-2 onco-protein was down-regulated." (PMID 34211462, 2021). "Western blots of MLL-ENL leukemia cells transduced with sgRNA for BCL2 or SOX4 are shown on the left." (PMID 34310280, 2021). "The therapeutic efficacy of BCL2 inhibitor has been reported in AML including MLL fusion-mediated leukemia." (PMID 34310280, 2021). "Preclinical data of genetic inhibition of BCL-2 gene showed promising results in a murine leukemia mouse model." (PMID 34830763, 2021). "Transcriptional upregulation of Bcl-2 in response to daunorubicin treatment has previously been demonstrated in leukaemia cell lines and plays a key role in increased resistance to chemotherapies." (PMID 33879127, 2021). "For instance, adipocytes present in the TME protected leukaemia cells from chemotherapy treatment by stimulating the expression of anti-apoptotic proteins BCL-2 and PIM2." (PMID 34829672, 2021). "Venetoclax, a selective inhibitor of the antiapoptotic protein B-cell lymphoma 2 (BCL-2), can lead to rapid initiation of apoptosis in leukemia cells." (PMID 33938209, 2021). "MYC, BCL2 rearrangements are rarely reported in precursor B-lymphoma/leukemia which carry dismal prognosis." (PMID 34307232, 2021). "Helenalin has been reported to cause apoptosis in various cells including renal carcinoma cells, CD4+ T cells and leukaemia cells, and to trigger necrosis in apoptosis-resistant cells such as Bcl-2 overexpressing leukaemia cells." (PMID 34959659, 2021). "It has been reported that costunolide induces mitochondria-mediated apoptosis, as demonstrated by the inhibition of Bcl-2, induction of Bax, and subsequent release of cytochrome c in various cancers, such as human prostate cancer and leukemia." (PMID 33669832, 2021). "In leukaemia, the balance of B‐cell lymphoma‐2 (BCL‐2) family proteins is disrupted, promoting survival of malignant cells and possibly LPC." (PMID 32452017, 2021). "Targeting BCL2 in the resistant cells leads to suppression of leukemia development in mouse models, which potentially provides an opportunity to treat patients that become resistant to FGFR1 inhibitors." (PMID 34734169, 2021). "ABT 263 (Navitoclax) is a chemotherapy drug that is used to induce apoptosis in cervical, esophageal, leukemia, and lung cancer cells by inhibiting the anti-apoptotic proteins, Bcl-2 and Bcl-xL." (PMID 33191466, 2021). "The reduced miR-15a/miR-16-1 induced leukemia cell apoptosis by targeting Bcl-2 plays the role of tumor suppressor genes." (PMID 34167441, 2021). "We also found that the level of pro-apoptotic bcl2-family members, Bax and PUMA in RAGE knocked down leukemia cells was higher than control group, while the level of anti-apoptosis protein Bcl2 was reduced." (PMID 34933679, 2021). "As the synergy between HDAC inhibitors and venetoclax (BCL2 inhibitor) was shown for patients with advanced-stage cutaneous T-cell lymphoma and glioblastoma, we researched this phenomenon in leukemia and NB sells." (PMID 34944663, 2021). "Taken together, these data support a mechanism in which a common leukemia-associated mutation, ASXL1, is linked to epigenetic upregulation of BCL2 expression and to enhanced sensitivity to VEN and AZA." (PMID 34548471, 2021). "Similar results were observed in leukaemia cells, with a further increase in BCL2 expression after 120 s of CAP exposure compared to 60 s." (PMID 34479596, 2021).
leukemia (continued). "High-throughput drug sensitivity and resistance testing revealed leukemia cells from RUNX1mut patients to be highly responsive for mTOR-, BCL2-, and VEGFR inhibitors and glucocorticoids." (PMID 32782381, 2021). "Surprisingly, while studying the ability of hydrazostat to induce apoptosis in leukemia and NB cells, we observed the differential regulation in BCL2 expression." (PMID 34944663, 2021). "Cobimetinib combined with venetoclax can play the therapeutic activity against leukemia, targeting both BCL2 and MAPK pathways to induce apoptosis of cancer cells." (PMID 34976824, 2021). "The combined expression of BCL2 with MYC induced leukemia in vivo with a penetrance similar to that with the MYC/HOXA9 combination, in accord with previous reports." (PMID 34310280, 2021). "Different authors demonstrated the cytotoxic effect of BCL2 inhibition in Ph- and Ph+ leukemia cells." (PMID 34884309, 2021). "In contrast, all MYC/BCL2-induced leukemias were of lymphoid lineage, the half of which was B-cell type, and the other half was T-cell type, consistent with a previous report." (PMID 34310280, 2021). "The cytotoxic effect of RSV in the leukemia cells was blunted by overexpression of Bcl-2 (CEM/Bcl-2), accompanied by increased COX activity and mitochondrial respiration." (PMID 34072396, 2021). "We previously discovered in vivo synergistic anti-leukemia activity of venetoclax and S63845, as each drug causes marked compensatory upregulation of MCL1 and BCL2 protein levels when used as single agent in zebrafish." (PMID 34331013, 2021). "On the other hand, Bcl2 deletion delayed the onset of leukemia induced by MLL-AF10 and the HOXA9/MEIS1 combination in vivo." (PMID 34310280, 2021). "Using this approach to guide our development of a series of ABT263-derived and VHL-recruiting PROTACs, we generate a potent BCL-xL and BCL-2 (BCL-xL/2) dual degrader with significantly improved antitumor activity against BCL-xL/2-dependent leukemia cells." (PMID 34824248, 2021). "BCL2 protein was enriched in leukemia progenitors and that cobimetinib inhibited cytokine-induced pERK and PS6 signaling pathways." (PMID 34976824, 2021). "In CAPE-treated HL-60 leukemia cells, caspase-3 was rapidly activated after 4 h, BCL2 expression decreased after 6 h and BAX expression intensified after 16 h." (PMID 32752091, 2020). "Bcl-2 plays an important role in progression of cancer and resistance to apoptosis and is usually increased in leukemia." (PMID 32587616, 2020). "Though previous studies demonstrated the inhibition potential of Bcl-2 by inducing antioxidant proteins in cancer cells, recent research has shown that Bcl-2 can promote ROS production in human leukemia cell lines, particularly." (PMID 33292641, 2020). "It has been shown that the inhibition of Bcl-2 selectively eliminates ROS-low quiescent leukemia stem cells but has little effect on ROS-high differentiated leukemia cells." (PMID 32998263, 2020). "The recognition that Bcl-2 promotes mitochondrial glycolysis to increase the survival of leukaemia stem cells led to the addition of a Bcl-2 inhibitor in the treatment regime for acute myeloid leukaemia." (PMID 32810419, 2020). "Protocatechuic acid or D1 has been recently reported to inhibit Bcl-2 protein expression and retinoblastoma phosphorylation in human leukemia cells." (PMID 32351610, 2020). "Underscoring the importance of mitochondrial integrity for survival and cell death in leukemia, synergistic effect of increasing intracellular chloride using moxidectin and antagonizing BCL-2 using navitoclax enhanced the cell death mechanism." (PMID 32591499, 2020). "In fact, the antiapoptotic function of PKC-α has been shown to be mediated by the phosphorylation of Bcl2 to promote cell survival, inhibit cell apoptosis and mediate drug resistance in leukemia." (PMID 32514253, 2020). "It is noteworthy that in addition to its role in liver fibrosis, BCL2 is known to play a critical role in leukemia." (PMID 32650615, 2020).
leukemia (continued). "The maintenance of leukemia stem cells depends on BCL2 mediated oxidative respiration, instead of glycolysis as in normal hematopoietic cells." (PMID 32571260, 2020). "In this scenario, hyper-activation of BCL-2 and increased autophagy mechanisms represent the main LSCs weapons, leukemia-specific, and therefore potentially druggable." (PMID 32486249, 2020). "Anti-apoptotic proteins like Bcl-2 and Bcl-xL were markedly upregulated in different types of leukemia malignancies, especially in more advanced MDS and in newly diagnosed AML, when compared to normal samples or AML patients under complete remission." (PMID 32486249, 2020). "Lee and co-workers also reported that anthocyanin, the derivative of the flavonoid family, which induces apoptosis of leukaemia U937 cells by down-regulating Bcl-2 expression." (PMID 32792514, 2020). "We showed that TXNIP overexpression increases sensitivity of leukemia cells to the Bcl‐2 and Bcl‐xL inhibitor, ABT263, by promoting apoptosis induction." (PMID 32511893, 2020). "A strong anti-leukemic activity has also been reported in MLL-fusion leukemia, through the down-regulation of fundamental pro-survival genes, such as BCL2, CDK6 and MYC." (PMID 33255367, 2020). "Previous reports indicated that GLP promotes the apoptosis of Human premortem leukemia cells (HL)-60 cells via regulating the expression of Bax, Bcl-2, and cleaved caspase-3." (PMID 32495637, 2020). "Bax and Bcl-2 conc ± SD and fold change levels for compounds 3a and colchicine on leukemia SR cell line." (PMID 32645912, 2020). "Low mir-15a expression has shown negative regulation by targeting Bcl-2 in human leukemia that is directly or indirectly involved in the biological process of apoptosis." (PMID 31456816, 2019). "Most importantly, also in this cohort we found that functional BCL-2 dependence of the leukemia cells measured by BAD-HRK priming is significantly associated with preclinical response predicting in vivo antileukemia VEN activity, in both BCP- and T-ALL." (PMID 31358732, 2019). "Given this heterogeneity of responses to VEN among different individual leukemias, we aimed to analyze markers indicating sensitivity to BCL-2 inhibition." (PMID 31358732, 2019). "The coexpression of Bcl-2 and P-gp confers resistance against the induction of apoptosis in leukemia cells originating from alterations in the lymphoid pathway of hematopoiesis." (PMID 31195716, 2019). "Intriguingly, the opposite effect is seen in the 697 leukemia cell line where overexpression of BCL2 protects these from paclitaxel-induced apoptosis." (PMID 31013740, 2019). "For example, the leukemia-associated R98S mutation in RPL10 (uL16) drives specific and constitutive IRES-mediated overexpression of the anti-apoptotic factor BCL-2." (PMID 30862070, 2019). "This alternative effect similarly observed in another leukemia cell line (HL-60) wherein extended treatment with both paclitaxel and vincristine have been shown to decrease BCL2 mRNA expression." (PMID 31013740, 2019). "Taken together, these data show that sensitivity to VEN is not only determined by presence of the target molecule BCL-2 alone but will rather be affected by the interaction of different BCL-2 family members present in the leukemia cell." (PMID 31358732, 2019). "Modeling clinical application of VEN in a preclinical trial in a set of individual ALL primografts, we identified that leukemia-free survival of VEN treated mice was precisely determined by functional BCL-2 dependence." (PMID 31358732, 2019). "As a consequence, leukemias carrying the RPL10-R98S (uL16-R98S) defect are highly sensitive to the clinically used BCL-2 inhibitor Venetoclax." (PMID 30862070, 2019). "Therefore, targeting BCL-2 could also be beneficial in leukemias with IL7Rα mutations." (PMID 29854301, 2018).